MET (MET proto-oncogene, receptor tyrosine kinase)
Description:
Receptor tyrosine kinase that transduces signals from the extracellular matrix into the cytoplasm by binding to hepatocyte growth factor/HGF ligand. Regulates many physiological processes including proliferation, scattering, morphogenesis and survival. Ligand binding at the cell surface induces autophosphorylation of MET on its intracellular domain that provides docking sites for downstream signaling molecules. Following activation by ligand, interacts with the PI3-kinase subunit PIK3R1, PLCG1, SRC, GRB2, STAT3 or the adapter GAB1. Recruitment of these downstream effectors by MET leads to the activation of several signaling cascades including the RAS-ERK, PI3 kinase-AKT, or PLCgamma-PKC. The RAS-ERK activation is associated with the morphogenetic effects while PI3K/AKT coordinates prosurvival effects. During embryonic development, MET signaling plays a role in gastrulation, development and migration of neuronal precursors, angiogenesis and kidney formation. During skeletal muscle development, it is crucial for the migration of muscle progenitor cells and for the proliferation of secondary myoblasts (By similarity). In adults, participates in wound healing as well as organ regeneration and tissue remodeling. Also promotes differentiation and proliferation of hematopoietic cells. May regulate cortical bone osteogenesis (By similarity). (Microbial infection) Acts as a receptor for Listeria monocytogenes internalin InlB, mediating entry of the pathogen into cells.
Synonyms: HGFR; RCCP2; DFNB97; AUTS9; DA11; c-Met
Tractability: Small molecule: an approved drug acts on it; a structure with a bound ligand is known; a high-quality ligand is known; it has a high-quality binding pocket; it belongs to a druggable protein family. Antibody: an approved drug acts on it; its Gene Ontology location is reachable by antibodies, with high confidence; UniProt places it where antibodies can reach, with medium confidence; UniProt predicts a signal peptide or a membrane-spanning region; the Human Protein Atlas places it where antibodies can reach. PROTAC: it is named in the literature on targeted protein degradation; UniProt records ubiquitination sites on it; ubiquitination databases record sites on it; its protein half-life has been measured; a small molecule that binds it is known. Other modalities: a drug acting on it is in phase 2 or 3 trials.
Target class: Enzyme; Tyrosine protein kinase Met family; TK protein kinase group; Kinase; Protein Kinase
Chemical probes: AMG-337 (high quality), BAY-474 (high quality), CAPMATINIB (high quality), GOLVATINIB, JNJ-38877605 (high quality), MK-8033 (high quality), PD081105, PD081191, PD081345, PD081416, PD081558, PD082005, PD082757, PD082867, PD083552, PD083593, PD084434, PD084959, PD085013, PD085048, and 26 more
Gene: Protein-coding gene on chromosome 7 (116,672,051 to 116,798,386, forward strand). Ensembl gene ENSG00000105976.
Subcellular location: Membrane; Secreted (Isoform 3)
Subcellular location (Human Protein Atlas): Plasma membrane; Cytosol; Predicted to be secreted
Pathways (Reactome):
Signal Transduction: Drug-mediated inhibition of MET activation; MET Receptor Activation; MET activates PI3K/AKT signaling; MET activates PTK2 signaling; MET activates PTPN11; MET activates RAP1 and RAC1; MET activates RAS signaling; MET activates STAT3; MET interacts with TNS proteins; MET receptor recycling; Negative regulation of MET activity; PI5P, PP2A and IER3 Regulate PI3K/AKT Signaling; PIP3 activates AKT signaling; RAF/MAP kinase cascade
Developmental Biology: Regulation of MITF-M-dependent genes involved in cell cycle and proliferation; Sema4D mediated inhibition of cell attachment and migration
Disease: Constitutive Signaling by Aberrant PI3K in Cancer; InlB-mediated entry of Listeria monocytogenes into host cell
Gene Ontology:
Molecular function: identical protein binding; molecular function activator activity; protein binding; protein phosphatase binding; hepatocyte growth factor receptor activity; protein tyrosine kinase activity; ATP binding; protein kinase activity; semaphorin receptor activity; transmembrane receptor protein tyrosine kinase activity
Biological process: branching morphogenesis of an epithelial tube; endothelial cell morphogenesis; hepatocyte growth factor receptor signaling pathway; negative regulation of hydrogen peroxide-mediated programmed cell death; positive chemotaxis; positive regulation of endothelial cell chemotaxis; positive regulation of transcription by RNA polymerase II; semaphorin-plexin signaling pathway; cell surface receptor protein tyrosine kinase signaling pathway; cell surface receptor signaling pathway; excitatory postsynaptic potential; liver development; negative regulation of autophagy; neuron differentiation; pancreas development; cell development; regulation of gene expression
Cellular component: basal plasma membrane; cell surface; membrane; plasma membrane; receptor complex; extracellular region; postsynapse
Genetic constraint (gnomAD): Loss-of-function variants: 49 observed, 139.54 expected, observed/expected ratio (o/e) 0.35, 90% interval 0.28 to 0.45. The upper end of that interval is the gene's LOEUF score, 0.45, which puts it in group 1 of 6, group 1 being the genes least tolerant of losing a copy. Missense variants: 1,440 observed, 1,783.4 expected, observed/expected ratio (o/e) 0.81, 90% interval 0.77 to 0.84. Synonymous variants: 626 observed, 650.66 expected, observed/expected ratio (o/e) 0.96, 90% interval 0.9 to 1.03.
Gene-disease validity (ClinGen):
ClinGen rates the evidence that MET causes each of these diseases.
papillary renal cell carcinoma (autosomal dominant): Definitive. A rare subtype of renal cell carcinoma, arising from the renal tubular epithelium and showing a papillary growth pattern, which typically manifests with hematuria, flank pain, palpable abdominal mass or nonspecific symptoms, such as fatigue, weight loss or fever.
nonsyndromic genetic hearing loss (autosomal recessive): Limited.
complex neurodevelopmental disorder (autosomal dominant): Disputed. A disorder that involves more than one phenotype associated with the central nervous system, including but not limited to intellectual disability, autism, and seizures (epilepsy).
Cancer hallmarks: escaping immune response to cancer (promotes); invasion and metastasis (promotes); genome instability and mutations (promotes); escaping programmed cell death (promotes); angiogenesis (promotes); proliferative signalling (promotes); escaping programmed cell death (suppresses)
Homologues: Orthologues: chimpanzee MET (99% identical), macaque MET (98% identical), pig MET (91% identical), dog MET (91% identical), mouse Met (89% identical), guinea pig MET (88% identical), rat Met (88% identical), rabbit MET (85% identical), tropical clawed frog met (64% identical), zebrafish met (52% identical). Paralogues in human: MST1R (34% identical), ROS1 (18% identical), MERTK (16% identical), AXL (16% identical), INSR (16% identical), RET (16% identical), IGF1R (15% identical), TYRO3 (15% identical), INSRR (14% identical), FGFR3 (13% identical), ALK (13% identical), FGFR2 (13% identical), and 41 more.
Diseases named in the same sentence as MET in open-access papers:
MET is named in the same sentence as 551 diseases in open-access papers, as found by Europe PMC text mining. Sharing a sentence is not in itself a finding about the gene and the disease. The quoted sentences say what the papers report.
lung cancer (746 papers, 2007 to 2026). A malignant neoplasm involving the lung. "In the lung cancer cohort, MET mutations exhibited high frequency of hotspots in front of the Kinase domain and within the Sema domain." (PMID 41521799, 2026). "Different MET mutation types were characterized, and somatic genomic mutational characteristics were examined across various MET mutation subgroups in both lung cancer and brain tumor cohorts." (PMID 41521799, 2026). "Lollipop plot illustrates the locations and protein domains of all MET gene SNVs and Indel mutations across the lung cancer cohort and the brain tumor cohort." (PMID 41521799, 2026). "In our study, we analyzed the spectrum of different MET mutation types in both the lung cancer and brain tumor cohorts and further examined the somatic genomic mutational characteristics across various MET mutation subgroups." (PMID 41521799, 2026). "In conclusion, this study will utilize multiplex immunohistochemical staining (mIHC) to provide a detailed characterization of the immune microenvironment in lung cancers harboring MET exon 14 skipping mutations." (PMID 40710213, 2025). "In the present study, we detected and found that there was no T790M mutation or other mutations including BRAF, PIK3CA, HER2 or c-MET amplifications in these resistant lung cancer cells." (PMID 39744423, 2025). "Here, we investigated the antibodies spontaneously elicited during breast and lung cancer that bind the cancer-associated antigen MET." (PMID 40401526, 2025). "Mesenchymal–epithelial transition factor (MET) inhibitors are used in patients with MET exon 14 skipping mutation‐positive lung cancer." (PMID 39671301, 2025). "Mutations in this domain have been confirmed in type 1 papillary renal cell carcinomas and even cause resistance to MET tyrosine kinase inhibitors in lung cancers and neuroblastoma." (PMID 40416971, 2025). "Outside the scope of lung cancer, it was also found that different MET exon 14 mutations predispose to diverse tumor types." (PMID 40361420, 2025). "Alterations in MAPK pathway genes with MET mutations decreased the MET inhibitor sensitivity in lung cancer." (PMID 39458991, 2024). "MET exon 14 skipping mutations have been reported to activate tumorigenesis and are found in 2–4% of non‐small cell lung cancer (NSCLC) cases." (PMID 38919814, 2024). "In patients with EGFR-mutated lung cancer, T790M mutations, MET amplifications, and other AGAs are among the acquired mechanisms of resistance to prior EGFR therapies, allowing for therapeutic options beyond chemotherapy." (PMID 39195317, 2024). "The HGF/c-MET axis is associated with Wnt/β-catenin signaling, with studies indicating that Wnt/β-catenin signals Snail1 and Zeb1 regulate bone metastasis in lung cancer." (PMID 39201787, 2024). "Alterations in the MET gene, including mutations, amplifications, and fusions, are implicated in the pathogenesis of various cancers, including lung cancers." (PMID 39199653, 2024). "Yet MET N375S, the most common polymorphism known to affect the MET gene and which causes an amino acid substitution in the semaphorin domain, is found also in several cancers, including lung cancers." (PMID 38652103, 2024). "In conclusion, MET gene alterations are associated with poor prognosis and resistance to standard treatments in lung cancers." (PMID 39199653, 2024). "The mesenchymal–epithelial transition (MET) factor, encoded by the MET gene, plays a crucial role in the cancer progression of non‐small cell lung cancer (NSCLC)." (PMID 39343987, 2024). "The second clinical observation was that tepotinib therapy can be effective in patients with MET exon 14 skipping mutations, including those with G‐CSF‐producing lung cancer." (PMID 38919814, 2024). "For example, whereas lung cancers are very often MET driven caused by the presence of MET exon 14 skipping mutations, MET-overexpressing head and neck squamous cell carcinomas are MET driven much more rarely." (PMID 38957115, 2024).
lung cancer (continued). "For example, MET amplification in lung cancer cells has been associated with an increase in the resistance potential of H1975 to ERL, possibly due to the crosstalk that has been demonstrated to exist between the two receptors." (PMID 39449797, 2024). "Nevertheless, a second-site mutation of EGFR Thr790Met, MET gene amplification, etc. confers lung cancer acquire resistance to these EGFR TKIs." (PMID 37004022, 2023). "Currently, TKIs of MET, such as crizotinib initially, and more recently capmatinib and tepotinib, have demonstrated clinical efficacy and safety in lung cancer patients with MET exon 14 skipping mutations and MET gene amplification." (PMID 37927472, 2023). "These mutations can change the structure and function of MET leading to different diseases such as lung cancer, neck cancer, colorectal cancer, and many other complex syndromes." (PMID 37200850, 2023). "We functionally disabled MET alleles in A549 human lung cancer cells by exploiting CRISPR-directed gene editing." (PMID 37345079, 2023). "The mutation of MET genes was closely related with multiple cancer, such as hepatocellular carcinomas, and lung cancer." (PMID 36817123, 2023). "We also demonstrated that MET inhibitors can overcome HGF‐induced resistance to EGFR tyrosine kinase inhibitors (TKIs) in EGFR‐mutated lung cancer cell lines." (PMID 36416133, 2023). "Both CDKN2A abnormalities and MET amplification are associated with the disease progression and poor prognosis of lung cancer patients." (PMID 36937524, 2023). "MET mutations indicate a tyrosine kinase mutation previously shown to be oncogenic and dysregulated in early-stage lung cancers." (PMID 35948941, 2022). "Altogether, these data suggest that the two novel MET variants (c.3028+3A>T and c.3012_3028del) identified in the lung cancer panel cause exon 14 skipping in the MET transcript." (PMID 36230737, 2022). "MET amplification is another major subtype of MET mutations which occur mainly in TKI-resistance lung cancer." (PMID 36619616, 2022). "Up to date, various mutations of MET have been identified, including MET amplification, MET point mutations, exon 14 skipping mutation, fusions and overexpression, all of which are oncogenic in lung cancer." (PMID 36619616, 2022). "It has been reported that CDH1 and ATM germline mutation was associated with colorectal cancer, and MET mutation plays an important role in lung cancer and colorectal cancer development and progression." (PMID 35372080, 2022). "Three advanced-stage NSCLC patients with one exon 14 and the other intron 14 novel MET variants were identified from an in-house lung cancer NGS test." (PMID 36230737, 2022). "Both EGFR and MET pathways have been implicated in driving tumor growth in lung cancer and in particular, MET pathway activation via upregulation of MET expression has frequently been described a mechanism of EGFR kinase inhibitor resistance." (PMID 34913823, 2022). "For example, the overexpression of the MET gene has been linked to the development and poor prognosis of lung cancer." (PMID 35631459, 2022). "This is consistent with the previous findings of MET mutated lung cancer and worsened outcomes with immunotherapy treatment." (PMID 34071259, 2021). "Several studies showed that in patients with EGFR-mutated lung cancer, osimertinib resistance can be promoted by MET amplification in around 20% of cases." (PMID 34298655, 2021). "We conclude that our new mouse strain mimics the osimertinib resistance observed in patients with EGFR-mutated and MET-amplified lung cancer." (PMID 34298655, 2021). "An important feature in patients with EGFR-mutated lung cancer and MET amplification is that they are resistant to osimertinib." (PMID 34298655, 2021).
lung cancer (continued). "Activation of the MET signaling pathway resulting from MET amplification or splice site alterations in MET exon 14 is associated with lung cancer growth and metastasis." (PMID 34733418, 2021). "In any case, we think that this is a very important finding because single treatment with anti-MET TKIs in patients with EGFR-mutated and MET-amplified lung cancer will restore EGFR activity." (PMID 34298655, 2021). "The MET exon 14 skipping mutation (METex14del) is found in 2%–3% of patients with non‐small cell lung cancer (NSCLC)." (PMID 33533182, 2021). "Increased FAM3C and MET copy numbers were tightly linked and correlated with increased gene expression and poor survival in human lung cancer and with extramural invasion in colorectal carcinoma." (PMID 33596971, 2021). "MET has been proposed as one of the driving oncogenes in lung cancer and the cause of drug resistance to EGFR TKIs." (PMID 33917539, 2021). "They established a gefitinib-resistant cell line model with MET gene amplification by exposing a gefitinib-sensitive lung cancer cell line (HCC827) with an activating EGFR mutation (exon 19 E746_A750 del) to increasing concentrations of gefitinib." (PMID 33572269, 2021). "Dysregulation of the MET pathway in lung cancer occurs via a variety of mechanisms including gene mutation, amplification, rearrangement, and protein overexpression." (PMID 33300283, 2021). "The present study offers a rationale to propose EGFR and MET inhibitors always in combination to patients with lung cancer harboring EGFR mutations and MET amplification." (PMID 34298655, 2021). "Skipping mutations in MET exon 14 were reported as they are present in ∼4.0% of patients with lung cancer/lung adenocarcinoma." (PMID 32435640, 2020). "The most frequent alteration is the MET exon 14 skipping mutation, which has been identified in 4% of lung cancers." (PMID 32549358, 2020). "Of the 21 patients, four (19%) lung cancer patients were treated with targeted therapy specifically for MET mutations (e.g., crizotinib, glesatinib)." (PMID 33437521, 2020). "Like that of MET exon 14 skipping mutations, the frequency of the MET amplification, 1.5%, in this lung cancer patient group are similar to those reported in other reports, ranging from 2% to 4%." (PMID 31369639, 2019). "The presence of MET exon 14 mutations in minor histological types of lung cancers urge to extend screening scope of this mutation in lung cancer and treatment response evaluation in clinical trials." (PMID 31369639, 2019). "The sensitivity of the established qPCR detection method for MET exon 14 skipping reached 0.1%, with the MET wild type transcripts being 1000X more abundant, and thus employed to screen the mutations in the lung cancer patient samples." (PMID 31369639, 2019). "In conclusion, MET exon 14 skipping mutation and gene amplification are both present in low frequencies, around 1%, in the studied lung cancer population." (PMID 31369639, 2019). "MET proto-oncogene, receptor tyrosine kinase (MET) associated with multiple diseases (such as lung cancer, hepatocellular carcinoma) in the focal adhesion pathway is a protein-coding gene." (PMID 31565070, 2019). "Mutations that lead to the skipping of exon 14 in MET have been detected in several cancers and are most prevalent in lung cancer at an incidence of about 3% in both Western and Asian countries." (PMID 29188469, 2018). "Occurrence of MET exon 14 skipping in lung cancer is mutually exclusive from other oncogenic driver mutations such as EGFR activating mutations, ALK fusion, and ROS1 fusion." (PMID 29188469, 2018). "Our study shows that treatment with naquotinib also induced in vitro MET amplification in lung cancers with EGFR mutations." (PMID 29386539, 2018). "In lung cancers, MET mutations are found in 3 to 10% of cases according to the ethnic origin, but in contrast to those found in renal cancers, they mainly affect the juxtamembrane domain." (PMID 28061464, 2017).